IRF1 (interferon regulatory factor 1)
Diseases named in the same sentence as IRF1 in open-access papers (continued):
Sharing a sentence is not in itself a finding about the gene and the disease.
pancreatic cancer (11 papers, 2018 to 2025). "Type II IFN (IFNγ) treatment can cause cell cycle arrest and inhibit the growth of pancreatic cancer cells by triggering caspase-1- and IRF1-dependent apoptosis." (PMID 35140750, 2022). "Recent investigations have illuminated the potential role of the IFN-γ/JAK/STAT1/IRF-1/procaspase-1 pathway as a pro-apoptotic mechanism in pancreatic cancer." (PMID 40909948, 2025). "IRF1 slows the growth of pancreatic cancer by preventing the synthesis of fatty acids and mitochondrial respiration." (PMID 38789431, 2024). "Taken together, we discovered that down-regulation of CTD-3252C9.4 facilitates pancreatic cancer progression via unbinding IRF1 to amplify IFI6 expression, hindering cell apoptosis and facilitating cell proliferation." (PMID 34399768, 2021). "Subsequent research using an in vitro model of pancreatic cancer has confirmed these clinical observations and thus, the tumor-suppressing and -promoting potentials of IRF-1 and IRF-2, respectively." (PMID 29599126, 2018). "Whereas IRF-1 expression is reduced in pancreatic cancer specimens compared with adjacent normal tissues, IRF-2 gene expression is up-regulated." (PMID 29599126, 2018). "Thereby, FOXP1 has a potential ability to bind to the IRF1 promoter region in pancreatic cancer." (PMID 36952469, 2023). "Our study demonstrated that CTD-3252C9.4/IRF1/IFI6 axis may be a novel therapeutic target in pancreatic cancer." (PMID 34399768, 2021). "Consistent with this, it has been proposed that increasing the IRF-1/IRF-2 ratio may serve as a novel therapeutic strategy for pancreatic cancer." (PMID 29599126, 2018). "Another study demonstrated that in pancreatic cancer, ZBED2 represses differentiation and dampens STAT2-mediated inflammatory response through IRES binding competition with IRF1." (PMID 36944729, 2023). "By binding to the transcriptional factor interferon regulatory factor 1 (IRF1), CTD-3252C9.4 prevents the transcription of IFI6, which ultimately induces pancreatic cancer cell apoptosis and represses cell survival." (PMID 34399768, 2021). "The involvement of IRF-1 and IRF-2 in the progression of human pancreatic cancer has also been reported." (PMID 29599126, 2018). "Our data indicated that CTD-3252C9.4 could promote pancreatic cancer cell apoptosis and restrain cell growth via binding IRF1 and preventing the transcription of IFI6, which may become a potential therapeutic target for pancreatic cancer." (PMID 34399768, 2021). "By binding to IRF1 to abolish its transcriptional activity, CTD-3252C9.4 inhibits the transcription of IFI6, which then leads to the activation of apoptosis signaling pathway in pancreatic cancer cells." (PMID 34399768, 2021).
glioblastoma (10 papers, 2014 to 2023). The most malignant astrocytic tumor (WHO grade IV). "We further found IRF1-regulated autophagy promoted glioblastoma resistance to bevacizumab treatment." (PMID 26362401, 2015). "It is possible that posttranslational modification of IRF1 is involved in bevacizumab-induced autophagy, which partly contributes to glioblastoma resistance to this therapy." (PMID 26362401, 2015). "Gene expression profile analysis performed on murine xenograft models of glioblastoma showed increased transcriptional levels of STAT1/IRF1 signaling in bevacizumab resistant tumors compared to control tumors." (PMID 26362401, 2015). "In our study, we found IRF1 down-regulation decreased autophagy and increased apoptosis in bevacizumab-treated glioblastoma." (PMID 26362401, 2015). "In particular, IRF1 expression was 33.893-fold higher in malignant glioma (p = 0.008); two additional studies by Liang and Bredel found that IRF1 expression was increased 2.225- and 2.151-fold, respectively, in glioblastoma." (PMID 33902005, 2021). "These cell lines were implanted into xenograft-bearing mice to determine whether IRF1 impacts the efficacy of bevacizumab therapy in glioblastoma." (PMID 26362401, 2015). "It is unknown if IRF1-regulating autophagy plays a role in glioblastoma resistance to bevacizumab therapy." (PMID 26362401, 2015). "Combined treatment of an IRF1 inhibitor and bevacizumab may increase the efficacy of antiangiogenic therapy on glioblastoma." (PMID 26362401, 2015). "Four candidate transcription factors (GATAD1, TEAD4, IRF1, and EGR2) were finally obtained and were found to be considerably highly expressed in specimens of patients with glioblastoma according to the results of qRT‐PCR and western blot." (PMID 36987665, 2023).
HIV-1 infection (10 papers, 2009 to 2025). The type species of lentivirus and the etiologic agent of acquired immunodeficiency syndrome (AIDS). "IRF-1′s crucial role in HIV-1 susceptibility was further supported by its upregulation by HIV-1 infection and the consequence of knocking down its expression using siRNA." (PMID 35336878, 2022). "In vitro studies that moderate reduction of cellular IRF-1 expression via small-interfering RNA (siRNA) by 30–60%, decreased in vitro susceptibility to HIV-1 infection by >95%." (PMID 35336878, 2022). "Another factor of the innate immune system, IRF-1, was recently implicated in the regulation of HIV-1 infection." (PMID 21994776, 2011). "Interestingly, specific IRF1 polymorphisms have been found in a small group of people showing resistance to HIV-1 infection and pathogenicity (non progressors)." (PMID 21994776, 2011). "NLRX1 can block STING-TBK-mediated antiviral responses in HIV-1 infection and support the early antiviral response by regulating IRF-1 abundance post-transcriptionally The NLRX1 gene can increase autophagy and reduce inflammatory responses." (PMID 41463370, 2025). "Our earlier work found that CD4+ T cells from Kenyan HESN female sex workers (FSWs) exhibit a lower basal level of IRF-1 but have the capacity for normal and transient IRF-1 response to HIV-1 infection." (PMID 35336878, 2022). "IRF-1 ubiquitination by HDM2 is specifically increased during HIV-1 infection in the presence of increasing amounts of Tat and is mediated by the formation of a trimeric complex between Tat, IRF-1, and HDM2, as demonstrated by coimmunoprecipitation analysis." (PMID 27795392, 2016). "IRF-1 expression was then evaluated after de novo HIV-1 infection of primary human CD4+ T cells; an early 2- to 3-fold stimulation of IRF-1 expression, was followed by an inhibition of IRF-1 expression to levels present in uninfected cells." (PMID 27795392, 2016). "In the context of HIV-1 infection, IRF-1 can act both as an inducer of viral gene expression and as an antiviral factor, depending on the physical interactions between Tat and IRF-1 in HIV-1-infected cells." (PMID 27795392, 2016). "The upregulation of RIG-I by HIV-1 infection in macrophages is novel and interesting, however its relationship with IRF-1 and IRF-7 regulation remains the subject of further investigation." (PMID 19404407, 2009). "We found that HIV-1 infection also induced interferon regulatory factor (IRF)-1, IRF-7 gene expression and signal transducers and activators of transcription 1 (STAT1) activation." (PMID 19404407, 2009). "Thus far, our earlier study showed that the IRF-1 genetic polymorphisms, found in approximately 72% of the HESN FSWs are associated with reduced IRF-1 expression, delayed IRF-1 response to IFN-γ and delayed establishment of HIV-1 infection." (PMID 35336878, 2022). "HIV-1 infection induced IRF-1 and IRF-7 gene expression and STAT1 phosphorylation in macrophages." (PMID 19404407, 2009). "HIV-1 infection induced IRF-1, IRF-7 gene expression and activated STAT1 in macrophages." (PMID 19404407, 2009). "IRF1 and IRF2 are ubiquitously expressed in cells, although they can be upregulated by type I IFNs and, in the case of IRF1, by TLR signaling and HIV-1 infection, illustrating how HIV-1 can coopt the antiviral IFN response to augment its own replication." (PMID 33472928, 2021). "Collectively, these results reveal that IRF-1 is dramatically downmodulated by increasing amounts of Tat, suggesting an active role of Tat in modulating IRF-1 expression and IRF-1-induced signature in T cells during HIV-1 infection." (PMID 27795392, 2016). "Of note, a recent study indicated that HIV-1 infection of MDDCs undermines the IFN induction pathway via interferon regulatory factor 1 (IRF1) and blocks type I IFN production, although HIV-1 infection in DCs induces a subset of ISGs." (PMID 21504576, 2011).
HIV-1 infection (continued). "The upregulation of IRF-1, IRF-7, and TRAIL, and the activation of STAT1 by HIV-1 infection was reduced by the treatment of type I interferon neutralizing antibodies." (PMID 19404407, 2009). "We have demonstrated that HIV-1 infection increased STAT1 phosphorylation at Tyr701 and total STAT1 expression and that the activation of STAT1 is essential for IRF-1 and IRF-7 expression and TRAIL induction." (PMID 19404407, 2009). "The role of IRF-1, IRF-7, type I IFNs, and STAT1 in the regulation of TRAIL during HIV-1 infection of macrophages is important and adds to our understanding of pathogenesis of HIV-1." (PMID 19404407, 2009). "Knocking down IRF-1 with siRNA decreased the HIV-1 infection levels, whereas the IRF-7 knockdown increased HIV-1 infection levels." (PMID 19404407, 2009). "The expression levels of IRF-1 and IRF-7 increased upon HIV-1 infection and the increase occurred as early as 3 days after infection." (PMID 19404407, 2009). "Nevertheless, our data strongly support a critical role for IRF-1, IRF-7, and type I IFNs in the induction of macrophage STAT1 activation during HIV-1 infection." (PMID 19404407, 2009). "Despite our extensive studies, we cannot exclude the potential roles of TLRs in the regulation of IRF-1 and IRF-7 during HIV-1 infection." (PMID 19404407, 2009). "In previous studies, we demonstrated that the host transcription factor IRF-1 is utilized early after de novo HIV-1 infection to initiate proviral transcription in the absence of expression of the viral Tat protein." (PMID 27795392, 2016). "Furthermore, the upregulation of IRF-1, IRF-7, TRAIL, and the activation of STAT1 by HIV-1 infection was reduced by the treatment of type I interferon (IFN)-neutralizing antibodies." (PMID 19404407, 2009). "When we applied siRNA to knockdown IRF-1, IRF-3, or IRF-7 gene expression in human macrophages, the increase of TRAIL expression by HIV-1 infection was reduced by the IRF-1 and the IRF-7 knockdown, but not by the IRF-3 knockdown." (PMID 19404407, 2009). "IRF-1 was also induced in T cells during early steps of HIV-1 infection and the expression of IRF-1 was also observed in non-permissive HIV-1 infection of DC." (PMID 21994776, 2011).
liver cancer (10 papers, 2014 to 2025). An epithelial or non-epithelial malignant neoplasm that arises from the liver. "Clinical data analysis showed a positive correlation between both METTL3/SRC and METTL3/IRF1, as well as the OS of liver cancer patients associated with METTL3/SRC expression." (PMID 40612868, 2025). "We hypothesized that the IRF1/c-Src axis was associated with the m6A-regulated development of liver cancer." (PMID 40612868, 2025). "We further provided evidence showing that IRF1 was a novel transcription factor of SRC, and the IRF1/c-Src axis participated in METTL3-promoted proliferation of liver cancer cells." (PMID 40612868, 2025). "Last, we proved that the upregulation of IRF1/c-Src expression participated in the METTL3-promoted cell proliferation of liver cancer." (PMID 40612868, 2025). "Consistently, similar results were obtained in colony formation assays using different liver cancer cells with silenced c-Src or IRF1 expression." (PMID 40612868, 2025). "We further confirmed that the IRF1/c-Src axis promoted the METTL3-regulated proliferation of liver cancer cells." (PMID 40612868, 2025). "Together, our results showed a critical role of the IRF1/c-Src axis in the METTL3-promoted liver cancer progression." (PMID 40612868, 2025). "A recent investigation into liver cancer has elucidated the role of IRF-1 in regulating the downstream factor HHLA2, facilitating immune escape, and promoting tumor progression." (PMID 40909948, 2025). "In summary, we showed that METTL3/IRF1/c-Src axis played oncogenic roles in the development of liver cancer." (PMID 40612868, 2025). "Not only that, studies have shown that EZH2 can also inhibit the expression of the immune checkpoint inhibitor PD-L1 by directly upregulating the levels of CD274 and IFN regulatory factor 1 (IRF1) promoter H3K27me3 in liver cancer cells." (PMID 37626362, 2023). "IRF1 has also been linked to a better prognosis in HCC, supporting a relevant role of IRF1 in liver cancer cells." (PMID 35453756, 2022). "Herein, we revealed that both IRF1 and c-Src showed promoted effects on the proliferation of liver cancer cells, hinting that either of them might be the potential target of liver cancer therapy." (PMID 40612868, 2025). "Results suggested that the METTL3/IRF1/c-Src axis played potential oncogenic roles in liver cancer development and the axis may be a promising therapeutic target in the disease." (PMID 40612868, 2025). "Since IRF1 unaffected the OS of liver cancer patients and c-Src acts as an effector in the METTL3/IRF1/c-Src axis, we further overexpressed c-Src in sh-METTL3 Huh7 and siMETTL2 HepG2 cells, respectively, to confirm the oncogenic role of METTL3/IRF1/c-Src axis in liver cancer cell proliferation." (PMID 40612868, 2025). "Notably, low levels of IRF-1 expression have been identified in liver cancer." (PMID 40909948, 2025). "Focusing on the transcriptional regulation of ISGs, recent findings in liver cancer indicate that the epigenetic modifier EZH2 can suppress PD-L1 expression by upregulating the level of H3K27me3 at the promoters of both the CD274 gene (which encodes PD-L1) and the IRF-1 gene." (PMID 40909948, 2025). "Previous studies suggest that miR-345 indirectly regulates transcription factors Slug, Snail, and Twist by targeting interferon regulatory factor 1 (IRF1), and activates the mTOR/STAT3/Akt signaling pathway, thereby slowing the EMT process of liver cancer." (PMID 38584703, 2024). "RANBP10, IRF1 and ZNF395 were found to be down-regulated in liver cancer tissues, while the expression levels of NACC1 and MLST8 remained unchanged." (PMID 24599008, 2014). "In addition, the expression of IRF1 was positively correlated to both SRC and METTL3 in liver cancer patients, p = 6.60 × 10−5 and p = 4.10 × 10−4, respectively." (PMID 40612868, 2025). "However, the expression of IRF1 showed a non-significant difference between liver cancer tissues compared to the control group." (PMID 40612868, 2025).
liver cancer (continued). "In addition, IRF1 level did not statistically affect the OS (p = 0.062) of liver cancer patients, which might be due to the comprehensive effects of IRF1 in cells." (PMID 40612868, 2025).
non-small cell lung carcinoma (10 papers, 2017 to 2024). A group of at least three distinct histological types of lung cancer, including non-small cell squamous cell carcinoma, adenocarcinoma, and large cell carcinoma. "Clinical research has revealed a significant correlation between IRF1 and the level of circulating IL-2, which is linked to the effectiveness and prognosis of chemotherapy for non-small cell lung cancer." (PMID 38915471, 2024). "A previous study suggested that metformin may be able to inhibit the function of Yes kinase-associated protein (YAP) in non-small cell lung cancer by preventing the binding of interferon regulatory factor 1 (IRF-1) and YAP promoter." (PMID 33849540, 2021). "This study aimed to investigate the expression and function of interferon regulatory factor-1 (IRF-1) in non-small cell lung cancer (NSCLC)." (PMID 35092496, 2022). "To examine genetic defects of the IFNγ-IRF1 pathway in non-small cell lung cancer (NSCLC), we analyzed The Cancer Genome Atlas (TCGA) lung adenocarcinoma (LuAd) and lung squamous cell carcinoma (LuSc) data." (PMID 28977839, 2017). "In non-small cell lung cancer cells, the W11R amino acid substitution was found in a variant of the IRF1 protein that failed to bind to DNA." (PMID 38396830, 2024). "IRF1 also played a role of tumor suppressor gene in non-small cell lung cancer (NSCLC)." (PMID 35464869, 2022). "IRF1 is also a potential tumor suppressor in non-small-cell lung cancer." (PMID 36589680, 2022).
endometrial cancer (9 papers, 2017 to 2025). Primary or metastatic malignant neoplasm involving the endometrium (mucous membrane that lines the endometrial cavity). "A previous study revealed that SPOP mutations promote tumor immune escape through the IRF1–PD-L1 axis in endometrial cancer." (PMID 40740763, 2025). "In contrast, endometrial cancer-associated SPOP mutants fail to degrade IRF1 and instead promote its stabilization, leading to enhanced PD-L1 expression." (PMID 40521202, 2025). "IRF1 is essential for tumor immune evasion caused by SPOP mutations in endometrial cancer." (PMID 38789431, 2024). "Functionally, endometrial cancer-associated SPOP mutations accelerate xenograft tumor growth, partially by augmenting IRF1 and PD-L1 levels." (PMID 40521202, 2025). "Recently, the SPOP has also been identified as a key negative regulator of the IRF1-PD-L1 axis in endometrial cancer." (PMID 40521202, 2025). "Recent studies have elucidated various mechanisms controlling PD-L1 abundance, such as transcriptional regulation by c-Myc in acute T-lymphocytic leukemia and IRF1 in endometrial cancer." (PMID 40483310, 2025). "We found that the genetic defects in the IFNγ receptor-IRF1 pathway genes in NSCLC occurred predominantly via a mechanism distinct from that in endometrial cancer." (PMID 28977839, 2017). "Similarly, inhibiting IRF1 has proven to boost immune surveillance in endometrial cancer and non-small cell lung cancer." (PMID 40483310, 2025). "To determine whether similar effects occur in endometrial cancer, we treated HEC-1A, RL95-2, and ECC-1 cells with baicalein at concentrations ranging from 2.5 to 80 μM for various durations and analyzed the expression of DDIT4 and IRF-1." (PMID 41303544, 2025). "Thus, unlike our previous finding in endometrial cancer where JAK1 frameshift was the predominant mechanism of the IFNγ-IRF1 pathway genetic defects, JAK2 gene deletion was the predominant mechanism of the IFNγ-IRF1 pathway genetic defects in NSCLC." (PMID 28977839, 2017).